EPO (erythropoietin)
Diseases named in the same sentence as EPO in open-access papers (continued):
Sharing a sentence is not in itself a finding about the gene and the disease.
polycythemia (continued). "We found that EPO-JAKPOT had high sensitivity (0.95; 95% CI 0.83–0.98) and a low −LR (0.07; 95% CI 0.02–0.30) for JAK2 mutant erythrocytosis, meaning that primary erythrocytosis could potentially be ruled out in an EPO-JAKPOT negative patient." (PMID 40806795, 2025). "However, while an elevated EPO level is not required for a diagnosis of secondary polycythemia, a majority of patients tend to have EPO levels much closer to the upper limit of 26 mU/mL than our patient." (PMID 40248540, 2025). "A significant rise in needless tests for diagnosis, such as EPO serum dose, molecular testing (JAK2V617 and exon 12), and bone marrow biopsies, may result from the isolated use of the suggested Hb/Hct levels as a description of polycythemia." (PMID 38511749, 2024). "If the serum erythropoietin level is low, PV should be considered and a quantitative JAK2 mutation assay should be obtained; if the serum erythropoietin level is high, secondary erythrocytosis should be considered and a JAK2 mutation assay is not necessary." (PMID 39598101, 2024). "This discovery could be significant for certain pathologies where the erythropoietic effect is not desirable, such as secondary congenital erythrocytosis where disease develops due to mutations in genes regulating Epo such as VHL, EGLN1, EPAS1, or EPO." (PMID 35682566, 2022). "Not surprisingly, in comparison to patients with PV, those with idiopathic erythrocytosis were more likely to be males and display lower white and platelet count, higher EPO levels, lower lactate dehydrogenase levels, absence of palpable splenomegaly or thrombosis." (PMID 34021251, 2021). "However, further studies with use of blood erythropoietin level, tissue erythropoietin detection using immune-stain and new molecular biology techniques need to be done and compared to uterine myoma patients with no erythrocytosis." (PMID 32190455, 2020). "In the patient with the mutation in PHD1 (EGLN2), sensitivity of erythroid progenitors to EPO and erythropoietin receptor (EpoR) activity were inappropriately increased and resulted in polycythemia with no or mild increase in EPO levels with increased EpoR expression." (PMID 30538672, 2018). "The normal kidney produces erythropoietin, rennin, and angiotensin; therefore it is not surprising that in 1–5% of hypernephroma cases there is an erythrocytosis owing to overproduction of erythropoietin, or hypertension arterial secondary to overproduction of rennin and/or angiotensin." (PMID 22919534, 2012). "Therefore, although leiomyomas produce erythropoietin, the serum erythropoietin level might not always be a reliable indicator of the degree of erythrocytosis." (PMID 24551466, 2014). "Had our study cohort been screened with EPO-JAKPOT, we would have ruled out JAK2-positive erythrocytosis in 130 patients (55%) without molecular testing at the cost of only 2 missed cases (1%)." (PMID 40806795, 2025). "We expect that EPO-JAKPOT would have even better negative predictive value in primary care and other settings with a lower prevalence of JAK2 mutant erythrocytosis than what was observed in our study." (PMID 40806795, 2025). "Therefore, we used erythrocytotic EPO Tg6 mice to understand the effects of only the EPO/polycythemia phenotype on epinephrine physiology without interference from the HIF2-PNMT pathway, and show that excessive EPO indeed increases urinary epinephrine excretion, thereby supporting our hypothesis." (PMID 34480587, 2021). "During the preceding seven years, bloodletting treatments were performed twice a month, because of severe polycythemia (RBC count: 5.95 million cells/μL; Haemoglobin: 14g/dl; haematocrit level >45%) without increased serum erythropoietin levels (18.8 mIU/ml)." (PMID 23816265, 2013). "Elevated EPO (>16.9 mU/mL) had a Sn of 0.16 (95% CI, 0.11–0.22), Sp of 1.0 (95% CI, 0.91–1.0), −LR of 0.84, and an infinite +LR for the diagnosis of JAK2 negative (secondary) erythrocytosis." (PMID 40806795, 2025).
polycythemia (continued). "However 1% of patients with PV are JAK2 negative, as the EPO level is not suppressed in 20% of cases, and the BM does not show panmyelosis in 10% of JAK2-positive erythrocytosis." (PMID 36611899, 2022). "However, erythrocytosis is uncommon in patients with NS and advanced CKD who are not treated with exogenous erythropoietin stimulating agents, and when present, will necessitate exploration of the other etiologies." (PMID 34449692, 2021). "We therefore conclude based on the low erythropoietin level and the BCR-ABL1 positivity, supporting the monoclonality of red stem cells, as well as the excellent evolution of erythrocytosis under imatinib therapy, that polycythemia without a high number of neutrophils may also be a feature of CML." (PMID 26187587, 2015).
Stroke (172 papers, 2007 to 2026). Sudden impairment of blood flow to a part of the brain due to occlusion or rupture of an artery to the brain. "Already in hemodialyzed patients, several investigators noticed that, as described for patients homozygous for the Chuvash mutation, pharmacological doses of EPO increase the risk for hypertension and stroke." (PMID 38672425, 2024). "Physically, the use of drugs like anabolic steroids, growth hormones, and erythropoietin is associated with cardiovascular problems, such as hypertension, heart attacks, and the occurrence of stroke." (PMID 39584970, 2024). "Mengozzi discovered that EGR2 and EGR4 were upregulated by neuroprotective erythropoietin in a model of middle cerebral artery occlusion, and this regulation was validated in stroke-related experiments, highlighting their association with ischemia." (PMID 38166990, 2024). "Future research using prospective method is needed regarding EPO level and clinical outcome in acute ischemic stroke comparing each stroke risk factor and the same blood collection time." (PMID 38302546, 2024). "EPO treatment can be associated with several side effects such as flu-like syndrome, hypertension, thrombosis, seizure, stroke, and hypokalemia, the most common of which is hypertension." (PMID 38029231, 2023). "The use of doping agents, such as anabolic steroids, stimulants, and erythropoietin, increases the risk of cardiovascular disease, thrombosis, stroke, and cancer in both genders." (PMID 38201954, 2023). "Examples include recombinant erythropoietin (EPO) for ischaemic stroke, where EPO and EPO analogues were associated with a decrease in infarct size and an improvement in various behavioural tests using multiple stroke models." (PMID 37360628, 2023). "Current guidelines suggest caution when initiating erythropoietin-stimulating agents in CKD patients with high risk of stroke." (PMID 37760839, 2023). "In line with our previous studies, EPO reduced infarct sizes, neurological impairments, and attenuated post-stroke weight loss over the observation period of 72 h." (PMID 34628598, 2022). "Studies have shown that high dosages of ESAs are strongly related to the risk of stroke, cardiovascular disease, cancer and, several clinical problems such as elevated blood pressure, anti-EPO effects, production of anti-EPO antibodies." (PMID 35318873, 2022). "Meanwhile, studies did not report a higher risk of adverse events, such as symptomatic thrombosis, deep thrombophlebitis, myocardial infarction, stroke, and hypertension, which were caused by the EPO intervention." (PMID 33928100, 2021). "On the other hand, data from the PREVEND study in patients with heart failure showed that higher EPO levels are associated with an increased risk of stroke in women." (PMID 32733466, 2020). "After loosening the erythropoietin payment criteria, a significantly lower risk of cardiovascular events, stroke, and heart failure hospitalization was observed in matched cohort 2, in particular for those with diabetes mellitus." (PMID 33331829, 2020). "The results of our study showed that administration of erythropoietin protects the brain against stroke, but this drug should be used with caution in high-risk individuals because of its side effects and possibility of stroke volume increase." (PMID 30719249, 2018). "For instance, EPO has been associated with increased mortality in severely ill stroke patients with a previous history of thromboembolic disease, including patients given thrombolytic treatment." (PMID 29673379, 2018). "Based on its potent neuroprotection and the fact that it is already widely used in clinical practice, especially in patients with anaemia associated with chronic kidney disease, EPO has been considered as a potential candidate for stroke treatment." (PMID 29438293, 2018).
Stroke (continued). "EPO resistance is a potential risk factor for mortality, cardiovascular disease, and stroke, which are associated with the high-dose use of EPO-stimulating agents and inability to achieve a target hemoglobin level." (PMID 26788441, 2016). "It is mentioned that EPO can directly reduce the risk of astrocyte swelling after stroke and other brain damages." (PMID 23493953, 2012). "Recombinant variant (rHu-EPO) has been evaluated for these purposes in different models of stroke such as in mouse, rat, gerbil, and rabbit, including global and focal cerebral ischemia, where it has shown convincing neuroprotective effect." (PMID 22701364, 2012). "In the current study, we found an association between EPO therapy and reduction of the incidence of 90-day recurrent stroke." (PMID 21269484, 2011). "• EPO therapy was significantly associated with a reduction in the incidence of 90-day recurrent stroke." (PMID 21269484, 2011). "Although previous studies had demonstrated that EPO reduces inflammation, cytokine production, fibrosis, and oxidative damage in the myocardium, chronic administration of EPO led to an increase in red blood cell mass and subsequent elevated stroke risk." (PMID 36741836, 2022). "The increased risk of thrombosis and stroke associated with EPO administration prompted researchers to design asialoerythropoietin, a desialytated version of recombinant EPO notable for its shorter half-life which allowed for its neuroprotective effects with limited effects on erythrocyte mass." (PMID 33796104, 2021). "It acts as neuroprotective against hypoxia and stroke, so low erythropoietin levels may induce the risk of neuronal damage and cognitive decline." (PMID 33312780, 2020). "However, it should be noted that in the early phase after stroke (6 h) EPO treatment reduced apoptosis rates in GRINA-deficient mice too." (PMID 31683519, 2019). "Indeed, EPO has been associated with increased mortality in severely ill stroke patients with previous thromboembolic disease, including patients given thrombolytic treatment." (PMID 30400939, 2018). "Therefore, in this study, we examined the erythropoietin pretreatment effect on blood glucose, inflammatory factors and its association with stroke volume and clinical outcomes." (PMID 30719249, 2018). "Besides, EPO therapy was significantly associated with a reduction in the incidence of recurrent stroke." (PMID 21269484, 2011). "However, non-haematopoietic EPO analogues remain as a therapeutic option for stroke, since the adverse effects of EPO were assumed to be mainly caused by its erythropoiesis stimulating effects." (PMID 20459870, 2010). "Brain-specific genetic ablation of the classical EPOR impairs post-stroke neurogenesis and neuronal survival whereas transgenic brain specific overexpression of human EPO is associated with reductions in postischemic infarct volume, brain swelling and functional deficits in a transient stroke model." (PMID 20142991, 2009). "The use of EPO has many benefits for patients with MHD, including improved quality of life and a reduced need for blood transfusion, but current studies have shown that the use of high doses of EPO may lead to an increased risk of stroke and all-cause mortality in MHD patients." (PMID 41244199, 2025). "Long-term administration of intravenous erythropoietin could cause thromboembolism and stroke." (PMID 40177652, 2025). "Using a high dose of EPO to reach the target hemoglobin level may increase the risk of stroke." (PMID 41244199, 2025). "Previous studies are also limited in the adjustment of possible confounders, such as stroke, risk factors for the cardiovascular system, erythropoietin, mean corpuscular volume (MCV), and red cell distribution width (RDW) that may be correlated with the mechanism which links anemia to dementia." (PMID 33312780, 2020).
Stroke (continued). "This analysis revealed that hS3 expression exceeded EPO expression in both ipsilateral and contralateral stroke hemispheres and in PPMS brains, whereas EPO predominated in ALS." (PMID 41602576, 2026). "Our study is the first to directly explore EPO and hS3 mRNA expression in human stroke, ALS and PPMS brains." (PMID 41602576, 2026). "Since EPO can cross the blood–brain barrier (BBB), peripheral administration of EPO has been investigated as a potential neuroprotective treatment in neurological disease models for stroke, multiple sclerosis (MS), and ALS." (PMID 41602576, 2026). "As reported by others, for six proteins we observed opposite directionality of associations for plasma versus CSF protein levels (APOE, EPO, PSMP, PRSS8 and TFPI with WMHs, IL-6 with HIP-PVS, and BT3A2 with stroke)." (PMID 41266628, 2025). "Experimental studies have suggested that erythropoietin has a neuroprotective effect and can promote neurological recovery after stroke." (PMID 41244199, 2025). "As follows, EPO doses (of 5000 IU each) given 48 and 72 h after the stroke showed neuroprotective benefits and durable improvements." (PMID 41012526, 2025). "The 2012 edition of the KDIGO Guidelines states that caution should be taken when treating MHD patients with a history of stroke with EPO." (PMID 41244199, 2025). "The use of EPO derivatives has been expanding alongside systematic monitoring of adverse effects—such as cardiovascular events, myocardial infarction, stroke, and renal failure—through rigorous clinical pharmacovigilance studies." (PMID 41012526, 2025). "Erythropoietin delivered from hyaluronan/methyl cellulose post‐stroke resulted in attenuated inflammatory response, reduced stroke cavity size, and promoted neurogenesis." (PMID 41244328, 2025). "So far, the angiogenic effect of EPO has been documented after an experimentally induced stroke or subarachnoid hemorrhage." (PMID 39355466, 2024). "Data analysis showed us in seventh day, median EPO in mild stroke was 814.6 (134.2–2988.9) pg/mL and in moderate stroke was 428.3 (239.5–980) pg/mL, and statistically, there was no significant differentiation." (PMID 38302546, 2024). "Systemically administered EPO has been shown to exert beneficial effects on rabbits subjected to subarachnoid hemorrhage and stroke, whereas intranasal administration of recombinant human erythropoietin (rHuEPO) protects rats against focal cerebral ischemia." (PMID 39355466, 2024). "So far, all studies concerning the angiogenic effect of EPO were performed after an experimentally induced stroke or subarachnoid hemorrhage." (PMID 39355466, 2024). "There have been previous studies using hyaluronan/methyl cellulose hydrogels for the delivery of erythropoietin after stroke injury." (PMID 39020197, 2024). "Systemically administered EPO has beneficial effects on rabbits subjected to subarachnoid hemorrhage or stroke." (PMID 39355466, 2024). "Another study on rats has also shown that chronic administration of EPO enhances neurogenesis and angiogenesis and improves neurological function in rats in vivo after an embolic stroke." (PMID 39355466, 2024). "Previous studies had reported that some medication categories are proven to exert an influence on the incidence of stroke, including erythropoietin, bevacizumab, tamoxifen, and antipsychotics, among others." (PMID 37020515, 2023). "Previous preclinical studies have shown synergistic effects on decreasing apoptosis and improving behavioral performance after stroke when combining two such trophic factors, erythropoietin (EPO) and insulin-like growth factor-1 (IGF-1)." (PMID 37763230, 2023). "In 2013, Asadi and colleagues succeeded in significantly reducing stroke severity scores after an acute ischemic stroke by administering EPO to the patients." (PMID 36879191, 2023). "In normal brain tissue, EPO is hardly expressed, but its content is significantly increased in stroke and can be used as a marker of brain damage." (PMID 36865742, 2023).